UBA6 (ubiquitin like modifier activating enzyme 6)
Diseases named in the same sentence as UBA6 in open-access papers (continued):
Sharing a sentence is not in itself a finding about the gene and the disease.
tumor (continued). "By contrast, the Uba6-null B16-GMCSF tumour showed a reduced tumour volume and improved survival in WT mice." (PMID 36109526, 2022). "We identify UBA6 functions as a tumour-intrinsic checkpoint that limits antitumour immunity and implicate UBA6 as an attractive target for immunotherapy." (PMID 36109526, 2022). "Authors show here that the purine metabolite inosine enhances tumour immunogenicity and thus immune checkpoint blockade therapy response by inhibiting the ubiquitin-activating enzyme UBA6 in tumour cells." (PMID 36109526, 2022). "Altogether, these data from immunotherapy-treated cancer patients support the clinical relevance of our experimental findings from mouse tumour models with UBA6 knockout, suggesting that UBA6 in tumour cells would be a useful target for immunotherapy." (PMID 36109526, 2022). "Unlike 4T1 and B16-GMCSF tumour cell models, inosine did not enhance T-cell-mediated tumour cell killing in inosine-pretreated MC38 tumour cell model, which have the relatively lower expression of UBA6 protein." (PMID 36109526, 2022). "On the one hand, the gut microbiota can directly enhance the innate immunogenicity of tumor cells by acting on UBA6 on the tumor cell surface to augment ICI responses." (PMID 35488243, 2022). "Together, our findings indicate that tumour cell-intrinsic proteins, especially UBA6, play a critical role in the effect of inosine on tumour immunogenicity." (PMID 36109526, 2022). "Our results demonstrate that inosine overcomes tumour cell-intrinsic resistance to immunotherapy by inhibiting UBA6 in tumour cells to enhance tumour immunogenicity." (PMID 36109526, 2022). "The dramatic biology of Uba6-null 4T1 and B16-GMCSF tumour-bearing mice was consistent with the relatively higher expression of UBA6 in these two tumour cell lines." (PMID 36109526, 2022). "To decipher the molecular mechanism of the UBA6 effect on tumour cells, we analysed the transcriptome of Uba6-null 4T1 cells and WT 4T1 cells by RNA-seq." (PMID 36109526, 2022). "Remarkably, enrichment analysis revealed that Uba6-null tumour cells had a marked increase in gene expression profiles evoked by inflammatory cytokines, such as TNF-α, IFNα, and IFNγ." (PMID 36109526, 2022). "The flow analysis proved the upregulated cell surface MHC-I protein expression in Uba6-null tumour cells, which was consistent with the effect of inosine." (PMID 36109526, 2022). "To further characterize tumor-like aggregate formation induced by UBA6 silencing, we isolated acini with normal appearance or gigantic cell aggregates from 3-D cultures, prepared cell suspensions from them, and incubated in conventional monolayer culture." (PMID 29152096, 2017). "Since only a fraction of these cells form gigantic cell aggregates, we postulated that cells with most efficient UBA6 knockdown accounted for the formation of tumor-like cell aggregates." (PMID 29152096, 2017). "MCF-10A cells stably expressing anti-UBA6 shRNA formed similar structures, but also developed a number (~5%) of tumor-like gigantic aggregates (shUBA6)." (PMID 29152096, 2017). "Inhibits UBA6 to enhance tumor immunogenicity and overcome ICIs resistance." (PMID 41181090, 2025). "Additionally, high inosine levels inhibited ubiquitin-like modifier activating enzyme 6 (UBA6) activity, increasing tumor immunogenicity and sensitivity to immune checkpoint inhibition." (PMID 40617808, 2025). "Recent studies have demonstrated that in vivo inosine and its derivatives could inhibit the activity of ubiquitin-activating enzyme 6(UBA6) to increase the immunogenicity of tumor cells, improving the tumor immunotherapy response." (PMID 39795180, 2024).
tumor (continued). "Inosine enhances tumor cell immunogenicity through the direct inhibition of UBA6 from tumor cells." (PMID 39267574, 2024). "In addition, inosine enhances tumor cell immunogenicity by inhibiting the activity of the ubiquitin activating enzyme UBA6, thereby improving the tumor immunotherapy response." (PMID 37266441, 2023). "However, inosine significantly increased the sensitivity of UBA6-overexpressed MC38 cells to T-cell-mediated tumour cell killing, compared to control MC38 cells." (PMID 36109526, 2022). "However, the effect of inosine in combination with ICB on tumour growth was abolished in Uba6-null B16-GMCSF tumour-bearing WT mice, compared with that of ICB treatment." (PMID 36109526, 2022). "In WT mice, Uba6-null 4T1 tumours were completely rejected within two weeks." (PMID 36109526, 2022). "In addition, proteomic profiles also confirmed the higher engagement of the IFN signalling pathway and inflammatory response signalling in Uba6-null tumour cells, showing consistency between our proteomic and transcriptomic data sets." (PMID 36109526, 2022). "While our study supports a pre-eminent role of UBA1 in determining the sensitivity of cSCC cells to MLN7243 under some circumstances suppression of UBA6 could contribute to the anti-tumour activity of this inhibitor." (PMID 29755650, 2018). "Therefore, controlling the expression of UBA1/UBA6 in tumors might regulate tumor TME and promote the killing effect of immune cells on tumors." (PMID 40046044, 2025). "Notably, Uba6 deletion in 4T1 cells reversed the effect of inosine on the expression of immune response-related genes, confirming the inhibitory effect of inosine on UBA6 in tumour cells." (PMID 36109526, 2022). "Thus, we provide evidence of an inosine-regulated UBA6-dependent pathway governing tumour-intrinsic immunogenicity and hence sensitivity to immune checkpoint inhibition, which might provide targets to overcome ICB resistance." (PMID 36109526, 2022). "Moreover, inosine can also enhance tumor immunogenicity and ICI efficacy through tumor cell sensitization to cytotoxic T cells in a UBA6‐dependent manner." (PMID 39031507, 2024). "UBA6 plays an important role in embryogenesis and multiple pathogeneses of diseases including cancer progression and metastasis, however, the impact of UBA6 on tumour-intrinsic immunogenicity has been never addressed before." (PMID 36109526, 2022).
cancer (9 papers, 2017 to 2025). A tumor composed of atypical neoplastic, often pleomorphic cells that invade other tissues. "Collectively, the phenotypes of UBA6-deficient mammary epithelial cells are analogous with those of anoikis-resistant invasive cancer cells." (PMID 29152096, 2017). "UBA1 and UBA6 are highly expressed in most cancer types, which may be associated with poor prognosis of patients." (PMID 40046044, 2025). "Finally, we analyzed the association between UBA1 and UBA6, and found that they were positively related with most cancers, especially PRAD and GBM, which indicated that they may modulate each other in the ubiquitination system to make it more sophisticated." (PMID 40046044, 2025). "UBA6 was positively correlated with RNAss in various cancers including ACC, LAML, PCPG and STAD, and negatively correlated with RNAss in CHOL and THCA." (PMID 40046044, 2025). "In contrast, UBA6 expression was positively correlated with these immune checkpoints in most cancers, including COAD, DLBC, KIRC, KIRP, LIHC, LUAD, THCA and UVM." (PMID 40046044, 2025). "We found markedly lower levels of tumoural UBA6 in cancer patients with partial response (PR), or stable disease (SD) compared to that in cancer patients with progressive disease (PD)." (PMID 36109526, 2022). "Together with recent studies, our findings highlight the potential application of inosine in combination with ICB for cancer patients with high UBA6 expression." (PMID 36109526, 2022). "Despite abnormal expressions in UBA6 being found in several types of carcinomas, the function of UBA6 in antitumour immunity and immunotherapy is unclear." (PMID 36109526, 2022). "Our OUT screens identified hundreds of potential substrates specific for UBA6-dependent ubiquitination, which will serve as a basis for elucidating more substrates that play key roles in epithelial cell biology and cancer development." (PMID 29152096, 2017). "Future studies based on the substrate profile from the OUT screens are expected to identify more Uba6-specific targets that are important for epithelial morphogenesis and human diseases including neuronal disorders and cancer." (PMID 28134249, 2017). "Besides, we also found that only CD276 was positively associated with UBA1 in most cancers, however, there are many other immune checkpoints like CD44, CD86 and CD274 illustrating a positive correlation with UBA6." (PMID 40046044, 2025). "This raises the possibility that under excessive inflammation, common in many cancers, hematopoietic cells may utilize the UBA6/FAT10 axis instead of the UBA1/Ub axis." (PMID 40588566, 2025). "While UBA6 has not been directly implicated in hematological malignancies, our findings suggest that UBA6 compensation may be involved in other cancers with dysregulated ubiquitin." (PMID 40588566, 2025). "In conclusion, UBA1 and UBA6 are critically involved in various diseases and cancers." (PMID 40046044, 2025). "CD276 expression was negatively with UBA6 only in a few cancers such as BRCA, COAD and READ." (PMID 40046044, 2025). "The opposite relationship between UBA1 and UBA6 in immune infiltration may account for the different prognosis of cancer patients." (PMID 40046044, 2025). "In addition, there are limitations inherent to our study with the modest numbers of cancer patients enroled to validate the predictive role of UBA6 for immunotherapy efficacy." (PMID 36109526, 2022). "However, the detailed molecular mechanism of how inosine modulates UBA6 and further details about the UBA6-dependent cell-intrinsic effects remain to be defined in cancer patients." (PMID 36109526, 2022). "Finally, we investigated the relationship between UBA6 expression and immunotherapy response in cancer patients." (PMID 36109526, 2022). "We separated cancer patients into two groups based on their tumoural UBA6 level." (PMID 36109526, 2022). "UBA6 is involved in brain development, cancer progression, and various physiological processes." (PMID 31067743, 2019).
cancer (continued). "However, exactly how UBA6 exerts its effect in cancer development needs to be further clarified." (PMID 31067743, 2019). "TAK-243 is a small molecular inhibitor of the proteins UBA1, UBA6 and NAE, used for cancer treatment in pre-clinical animal models." (PMID 36293188, 2022). "Here we demonstrate that UBA6 plays unique roles in suppressing EMT, a critical step of cancer progression toward invasion and metastasis." (PMID 29152096, 2017). "In pan-cancer, the total expression level of UBA1 was higher than that of UBA6." (PMID 40046044, 2025). "Lastly, our Uba6/Ub-AMP structures, and in particular, differences with the human Uba1 active site, will provide a framework for drug discovery efforts targeting specifically this enzyme for therapeutic intervention in cancer and other diseases." (PMID 35986001, 2022). "In contrast, HMCES, UBA6, and ATXN7L3 appeared to have a more restricted pattern of sensitization to DNA damaging agents, indicating that they may represent better targets for selective killing of APOBEC-expressing cancer cells." (PMID 33788831, 2021).
bacterial infection (1 paper, 2019). "UBA6-mediated FAT10ylation has also been implicated in targeting proteins for proteasomal degradation as well as in the intracellular defense against bacterial infection." (PMID 31692446, 2019).
gastrointestinal tumors (1 paper, 2025). "Importantly, our observations uncover a novel ubiquitination cascade composed of UBA6, UBE2Z, and FBXW7 that may regulate the degradation of the squamocin‐induced EZH2/MYC axis in pan‐gastrointestinal tumors." (PMID 39823459, 2025).
UBA6 also shares sentences with these, for which no sentence is quoted: colon cancer (2 papers); gastric cancer (2); Autoimmunity (1); colorectal cancer (1); diabetes mellitus (1); glioblastoma (1); hematological malignancies (1); hereditary hemochromatosis (1); myeloma (1); neurodegenerative disease (1); oesophageal cancer (1); renal carcinoma (1); renal cell cancer (1); stomach cancer (1).